MIR676 (microRNA 676)
Synonyms: hsa-mir-676; mir-676
Gene: MicroRNA gene on chromosome X (70,022,857 to 70,022,923, forward strand). Ensembl gene ENSG00000211991.
Gene Ontology:
Biological process: miRNA-mediated post-transcriptional gene silencing
Cellular component: RISC complex
Homologues: Orthologues: chimpanzee MIR676 (100% identical), macaque mml-mir-676-1 (96% identical), pig ssc-mir-676-1 (87% identical), rat Mir676 (85% identical), dog MIR676 (79% identical), rabbit MIR676 (78% identical).